CCL2 (C-C motif chemokine ligand 2)
Diseases named in the same sentence as CCL2 in open-access papers (continued):
Sharing a sentence is not in itself a finding about the gene and the disease.
cancer (continued). "Therefore, some chemokines such as CCL2, CXCL10, and CX3CL1/CX3CR1 can be either favorable or unfavorable cancer prognostic factors depending on the cancer types." (PMID 31991604, 2020). "However, we find that CCL2, PARP1 are highly expressed at least in the Basal-type cancers, the majority of which falls into the TNBC category." (PMID 32455851, 2020). "The increasing number of studies indicate that neutralization of CCL2, acting via CCR2, might be effective in attenuating neuropathic pain and cancer pain." (PMID 33408720, 2020). "Correlation of MYC+TWIST1 expression with CCL2 and IL13 in TCGA pan-cancer cohort (n = 9502)." (PMID 31933479, 2020). "Inhibiting two cytokines known as CCL2 and IL13 prevented the cancer cells from moving." (PMID 31933479, 2020). "The CC chemokines, such as CCL2, CCL11, CCL16, and CCL21, which are major determinants of macrophage infiltration and angiogenesis, have been demonstrated to function in the cancer of breast, lung, esophagus, ovary and cervix, and CCL2 primarily contributes to the recruitment of macrophages." (PMID 32161718, 2020). "Further, our results suggest that Ccl2 and Il13 alone can enable a non-metastatic cancer to become metastatic, cell non-autonomously." (PMID 31933479, 2020). "Several studies have documented cross talk between cancer and immune cells, but also inflammatory factors that are expressed by the TME, such as the CSF family of cytokines, which attract macrophages (through CCL2 and VEGFA)." (PMID 33036138, 2020). "Moreover, in 33 different human cancers, expression of both MYC and TWIST1 predict survival, expression of CCL2/IL13 and M2-like TAM infiltration." (PMID 31933479, 2020). "Heatmap of differential gene expression in GGN-ADC and SADC showed that some cancer-promoting genes, such as HSPB1, CCL2, CXCL14, MDK, and MMP7, were highly expressed in SADC, indicating that the cancer cells derived from SADC had a higher malignant degree than those derived from GGN-ADC." (PMID 33083004, 2020). "Prosurvival cytokines including IL 8 and MCP1/CCL2 were secreted by MSCs into BCP-ALL cells via TNTs signaling, which resulted in chemoresistance of BCP-ALL cells against prednisolone, a glucocorticoid drug used in cancer therapy to induce apoptosis." (PMID 32423160, 2020). "Even though there is no previous evidence in the literature for CCL7 abolishing immunoglobulin expression specifically during cancer progression, it was reported that MSC–derived CCL2 suppresses plasma cell immunoglobulin production via STAT3 inactivation and PAX5 induction." (PMID 30764543, 2019). "Unlike commonly used cargo-carrying, vector-directed drug delivery vehicles, CCTV nanoparticles may act as therapeutics/theranostics themselves, particularly in inflammatory conditions with CCL2/CCR2 pathogenesis, including cardiovascular disease and cancer." (PMID 31723548, 2019). "Next, we knocked out the CCL2 gene by CRISP/Cas9 editing technique in CT26 and MC38 cancer cells." (PMID 31780645, 2019). "Inhibitors of the axes of CXCL8, CCL2 and CCL5 and their receptors are also available, suggesting that treatments of TNBC cancers with combination therapies of chemokines and pro-inflammatory cytokines may provide novel treatment options for TNBC patients." (PMID 31031757, 2019). "CCL2 and CCL5 also promote cancer cell growth, survival, migration and EMT." (PMID 31484464, 2019). "Inhibition of CCR2/CCL2- and CSF-1R-dependent signaling pathways is a major focus in this field, as direct targeting of CCR2/CCL2 showed positive outcomes in various experimental cancer models." (PMID 31547627, 2019). "Notably, our study also found a novel reciprocal activation between cancer cells and TAMs that FoxQ1 expression in CRC cells co-cultured with TAMs promoted macrophage attraction in a CCL2-dependent manner." (PMID 30927925, 2019). "We found that already at these early stages of progression, HER2+ cancer cells upregulated expression of Ccl2 but not Csf2, Csf1, Il1β, and Il6." (PMID 29295986, 2018).
cancer (continued). "Mechanistically, we show that, in pre-malignant lesions, CCL2 produced by cancer cells and myeloid cells attracts CD206+/Tie2+ macrophages and induces Wnt-1 upregulation that in turn downregulates E-cadherin junctions in the HER2+ early cancer cells." (PMID 29295986, 2018). "Under in vitro conditions, they stimulated cancer cell proliferation (via IL-6), migration (via CXCL8/IL-8 and CCL2/MCP-1), and invasion (via IL-6, MMP-3 and uPA), and they triggered the EMT in a mechanism involving TGF-β1-dependent induction of Smad 2/3-Snail1 signaling." (PMID 28956065, 2018). "Moreover, CCL2 induces the expression of ICAM1 on human lymphatic endothelial cells and facilitates the attachment of cancer cells to lymphatic endothelial cells." (PMID 30585203, 2018). "Here the mechanism of pleural IL-1β function in MPE promotion is elucidated: CCL2-attracted monocyte-released IL-1β fosters NF-κΒ activation of MPE-prone KRAS-mutant carcinomas by potentiating non-canonical NF-κB signaling via IKKα." (PMID 29445180, 2018). "CCR2 ligands, CCL2, CCL7, and CCL12, are produced by various cell types, including cancer cells." (PMID 29170400, 2017). "On the basis of CVC mainly blocking the migration of circulating monocytes to inflamed tissue via the CCL2/CCR2 axis, future studies might even address a broader range of inflammatory diseases as well as cancer." (PMID 28910354, 2017). "Subsequently, p-STAT3 can induce the downstream target genes, such as CCL2, CCL5, ICAM-1, SNAI1, chitinase-3-like 1 (CHI3L1), FBJ murine osteosarcoma viral oncogene homolog (FOS), and Skp2, that promote various cellular processes for cancer progression." (PMID 28157698, 2017). "Moreover, GO analysis suggested that up-regulated CCL2 participated in the chemokine signaling pathway, and down-regulated NOS2 involved cancer and calcium signaling pathways." (PMID 28095896, 2017). "CCL2-neutralizing antibodies, which have shown promising therapeutic efficacy in several cancer models, are not widely used due to technical issues." (PMID 28424406, 2017). "Interestingly, we’ve demonstrated that RT rapidly, and with varying kinetics, increases the production of CCL2 and CCL5 across several different murine and human cancer cell lines in vitro." (PMID 27852031, 2016). "Inflammatory chemokines, such as C-C chemokine ligand 2 (CCL2), are often present in tumors but their roles in cancer initiation and maintenance are not clear." (PMID 27820834, 2016). "Additionally, CCL2 induces expression of metalloproteinases MMP2 and MMP9 in cancer cells, leading to increased invasion." (PMID 26885690, 2016). "In murine models, it has been verified that blocking CCL2/CCR2 signal pathway could restraint the infiltration of macrophages and postpone cancer metastasis." (PMID 27409666, 2016). "We found blockade of EGF/EGFR axis reduced the expression of CCL2 in Cal27 cells, while suppression of CCL2/CCR2 axis decreased the expression of EGF in THP1 cells, suggesting that in HNSCC, the crosstalk between cancer cells and macrophages was also mediated by a positive feedback paracrine loop." (PMID 27888616, 2016). "Our above results reminded us that Cal27-derived CCL2 and THP1-derived EGF might form a positive feedback loop, thus promoting the differentiation of macrophages and the invasion of cancer cells." (PMID 27888616, 2016). "In cancer cells, decreased miR-126/126* expression results in an increased production and secretion of CXCL12 that in turn attracts MSCs to the tumor microenvironment and increases the secretion of CCL2." (PMID 25743773, 2015). "Similarly, treatment of Caski and CSCC1 cancer cells with entinostat resulted in a higher production of CCL2, IL-8 and CXCL9 by the cancer cells when stimulated with IFN-γ and TNF-α than dimethylsulphoxide carrier control-treated cells." (PMID 26055519, 2015). "CCL2 has been shown to be pivotal for immunosuppression, and the CCL2/CCR2 pathway could be a potential target for cancer therapy." (PMID 26683520, 2015).
cancer (continued). "CCL2/MCP-1 plays a key role for immunosuppression, so that inhibition of CCL2/CCR2 pathway could be a possible approach for cancer treatment." (PMID 25333973, 2014). "Cancer cells undergoing angiogenic switch also produce chemoattractants and mitogens, including HIF1-α (hypoxia-inducible factor 1-alpha), VEGF, FGF-1, CCL2 (C-C motif chemokine 2), and CXCL12 (stromal cell-derived factor 1), for endothelial cells and proangiogenic immune cells." (PMID 23717341, 2013). "MCP-1/CCL2 plays an important role in the initiation and progression of cancer." (PMID 23527025, 2013). "Our gene expression analysis seems to support both hypotheses, as besides CCL2, CCL3 and CCR5 up-regulation, we also observed increased expression of MMP-9 in cancer cells grown under co-culture conditions with macrophages." (PMID 22353646, 2012). "However, we did not observe a ZEB1-dependent effect on proliferation of CD8 + T cells in vitro when co-cultured with BMDMs, but a ZEB1-dependent modulation of CD8 + T cell migration by CCL2 and CCL22 as well as CCR2 and CCR4 expression in CD8 + T cell subsets in murine and human cancers." (PMID 40595293, 2025). "Given the major role of CCL2 in immunosuppressive processes, combinatorial approaches involving ion channel modulators and CCR2 antagonists or immune checkpoint inhibitors may yield synergistic benefits in cancer treatment." (PMID 40806751, 2025). "CCL2 induces the recruitment of ILC3s to tumors and stimulates the production of CXCL13 by tumor stromal cells, which ultimately leads to the production of the cancer cell motility factor receptor activator of NF-κB ligand and promotes lymphatic metastasis of breast cancer cells." (PMID 39309440, 2024). "NK cells with reduced anti-cancer functions in the immunosuppressive lung tumor microenvironment acquire pro-cancer properties and begin to produce and secrete VEGF and CXCR2 ligands such as CXCL1, CXCL2, and CXCL8/IL-8 as well as IL-6, CCL2, matrix metalloproteinases (MMP), and many others." (PMID 38673949, 2024). "In addition, given the correlation between the density of TAMs and cancer prognosis, blocking the recruitment of macrophages in TME, for instance through ablation of CCL2/CCR2 axis, has been shown to be an effective therapeutic strategy to reduce the density of protumor TAMs and improve prognosis." (PMID 39003350, 2024). "Additionally, we found that ANXA9 could transfer the S100A4 out of cancer cells and down regulation of ANXA9 could decreased the cytokines of IL-6, IL-8, CCL2, and CCL5." (PMID 38609357, 2024). "Considering the significant role of the CCR2 receptor in cancer, in this study, for the first time, we studied the effect of this compound in preventing the development of CRC in mouse models and cell lines through inhibition of the CCR2_CCL2 signaling pathway." (PMID 37325423, 2023). "Therefore, anti-TIF1-γ antibodies, VEGF-A, TNF-α, CCL2, IL6, and IFN-γ could have essential roles in indicating the presence of cancer in anti-TIF1-γ antibody-positive DM patients." (PMID 36357631, 2023). "Additionally, FJX1 expression was significantly and positively correlated with immunosuppressive genes (TGFB1 and IL-10), chemokines (CCR1 and CCR5), chemokines receptors (CCL2 and CXCL5), and immunosuppressive pathway-related genes (TFGB1 and WNT1), in most TCGA cancers." (PMID 37324001, 2023). "Interestingly, among pan-cancer, LGG showed the most significant correlation between GLA with CD86 (P=4.52e-27), CSF1R (P=8.17e-09),CCL2 (P=3.98e-14), CD68 (P=2.37e-34), IL10 (P=3.29e-21), IRF5 (P=8.5e-25), CD163 (P=3.8e-26), VSIG4 (P=9.17e-16) and MS4A4A (P=1.39e-21)." (PMID 37057282, 2023). "Interestingly, apoptotic cancer cells release epigenetically regulated cytokines including CXCL10 and CCL2, enhancing nucleic acid-elicited phagocytosis of dying cancer cells by neutrophils, providing alternative approaches for neutrophil-based anticancer therapy." (PMID 37928272, 2023).
cancer (continued). "CCL2 could recruit CD206hi macrophages and increase Wnt-1 production from those cells, which led to decreased levels of E-cadherin in the HER2+ cancer cells, resulting in the early dissemination of cancer cells." (PMID 36674955, 2023). "Therefore, we hypothesized that VEGF-A, TNF-α, CCL2, IL-6, and IFN-γ could distinguish cancer among anti-TIF1-γ antibody-positive DM patients." (PMID 36357631, 2023). "In addition to Kras, Ccl2, and Il1b, a battery of other transcripts originated within the signature of KRAS-mutant cancers derived from the transcriptomes of our cell lines, providing synthetic lethality candidates for in vivo KRAS dependency for future research." (PMID 35327394, 2022). "In one study, a water JCo extract inactivated the PI3K–Akt pathway in cancer cells, and our data revealed that JCo extract suppressed NFκB expression and the downstream expression of chemokines and cytokines such as TNF‐α, IL‐1β, IL‐6, and CCL2 in the rat renal cell line NRK‐52E." (PMID 36249972, 2022). "We identified that targeting CCR4 could effectively interrupt the activation of HNSCC invasion and metastasis induced by CCL2 without the promoting cancer relapse observed during the subsequent withdrawal period." (PMID 35177591, 2022). "At the same time, IHC staining in transplanted tumors indicated that the CCR4 antagonist could effectively downregulate the phosphorylation of Vav2 and MLC in cancer cells, but not in tumors treated with CCL2 neutralizing antibody." (PMID 35177591, 2022). "Tumor-derived C–C motif chemokine ligand 2 (CCL2) binds to CCR2+/Ly6Chi endothelial cells to increase vascular permeability and recruit inflammatory monocytes in a p38/MAPK-dependent manner, thereby promoting the extravasation and seeding of metastatic cancer cells." (PMID 36313280, 2022). "In addition, OSCAR expression was positively correlated with infiltrating levels of TAMs in 20/20 types of cancer, especially BRCA (CCL2, r=0.428; CD68, r=0.769; IL10, r=0.542), COAD (CCL2, r=0.561; CD68, r=0.624; IL10, r=0.536), and THCA (CCL2, r=0.612; CD68, r=0.870; IL10, r=0.597)." (PMID 34093786, 2021). "The addition of 786O cancer cells led to an increase in MMP9, Gro-α, IL-8, IL-6, HB-EGF, and VEGF-A; and the addition of ccRCC PBMCs led to an increase in PDGF-BB and IL-1β as well as a further increase in MMP-9, Gro-α, IL-8, IL-6, and CCL-2 despite cabozantinib treatment." (PMID 34931665, 2021). "Although the truncated isoform is less able to attract eosinophils and monocytes, it could not antagonize CCL2 in monocyte chemotaxis, which is a major monocyte attractant in cancer." (PMID 34503058, 2021). "In view of the rather disappointing developmental history of CCR2 antagonism, and the now increased understanding of mode of action of the CCL2/CCR2 axis, we attempt to discuss the strategies that could facilitate tailored application of CCR2 antagonism in cancer therapy." (PMID 34804061, 2021). "Moreover, ECM proteases such as urokinase plasminogen activator and its soluble receptor are activated at injury sites of cancer cell invasion and contribute to the attraction of interacting MSC in coordination with interleukins (IL-6 and IL-8) and monocyte chemoattractant protein-1 (MCP-1 = CCL2)." (PMID 32751163, 2020). "Finally, in iCCA xenograft model, CCL2 stimulated cell proliferation, induced angiogenic factors (VEGFA, MMP2, MMP9, MMP12, Angiopoietin II) and mediated migration of MDSCs, macrophages and other immune cells, promoting cancer growth." (PMID 32784743, 2020). "Additionally, these junctions can be destabilized by the expressions of cytokines, chemokines, and inflammatory mediators, including VEGF, basic FGF (bFGF), TGF-ß, IL-1ß, TNF-α, interferon-γ (IFN-γ), CCL2, CXCL8, and prostaglandin-endoperoxide synthase 2 (COX2), by the cancer cells." (PMID 31900168, 2020).
cancer (continued). "There are also a number of studies, that report either that serum CCL2 levels in cancer patients are not related to clinical variables or that higher serum CCL2 levels are associated with a better prognosis and/or that lower serum CCL2 levels are associated with worse prognosis." (PMID 31823764, 2019). "The purpose of this review is to explore the role of monocyte chemoattractant protein-1 (MCP-1 or CCL2) in the processes that underpin bone remodelling, particularly the action of osteoblasts and osteoclasts, and its role in the development and metastasis of cancers that target the bone." (PMID 31713180, 2019). "In the subsequent steps of cancer progression as in High-grade Squamous Intraepithelial Lesion (HSIL), cancer cells mold their stromal neighbors in chemo-attractors for dendritic cells and macrophages via the activation of CCL2/C-C motif Chemokine Receptor (CCR)." (PMID 31096567, 2019). "Therefore, we used ELISA for a subset of leukocyte chemokines ‐ CXCL8 (neutrophils), CCL2 (monocytes) and CCL5 (T‐cells) to determine whether cancer cells or NTF were the main chemokine producers." (PMID 30191960, 2019). "We found PSMP could be produced by PCa cells but not by macrophages, which was different from CCL2 produced by macrophages, endothelial cells, and cancer cells." (PMID 31555577, 2019). "Open Science Framework: CCL2 and IL18 expressions may associate with the anti-proliferative effect of noncontact electro capacitive cancer therapyin vivo." (PMID 32695310, 2019). "The increased concentrations in the TME of cytokines and growth factors such as CCL2, IL-1β, M-CSF, TGF-β, and VEGF, induced by cancer cells and the intervention of the immune system, promote the enlistment of CAFs and TAMs as contributors of nutrients and growth factors needed by cancer cells." (PMID 30627563, 2018). "In this model, however, cancer cells may not be a major source of CCL2 since the number of TAMs does not correlate with mRNA levels of human CCL2 in MDA-MB-231 cells but does with mouse Ccl2 in the stroma." (PMID 30483271, 2018). "TAMs, recruited by chemokines CCL2, CCL5, and CXCL, are derived from circulating monocyte precursors and are the most important regulators of tumorigenesis, which may serve as one of the hallmarks of cancer." (PMID 28243242, 2017). "Furthermore, Oligo-Fucoidan supplementation increases cancer cell death and attenuates the adverse effects induced by etoposide that decreases production of the pro-inflammatory cytokine IL-6 and chemokine CCL2/MCP-1." (PMID 28928376, 2017). "In addition, the higher ratios of IFNα2 to Th2 cytokines, including IFNα2/IL4, IFNα2/IL10, IFNα2/CCL2, IFNα2/CCL7, IFNα2/CCL11, and IFNα2/TNFα, were associated with increased odds of ER negative vs. ER positive cancer." (PMID 24473087, 2014). "CCL2 expression was lower in most tumors relative to normal tissues, which may stem from differences in the degree of immune infiltration of tumors such that monocyte and macrophage chemotaxis was not achieved to the same extent in all cancer types." (PMID 40535567, 2025). "We determined the cut-off values, sensitivities, and specificities of VEGF-A, TNF-α, CCL2, IL-6, and IFN-γ as biomarkers to investigate whether their plasma levels could distinguish cancer in anti-TIF1-γ antibody-positive DM patients and reflect the presence of cancer through the ROC curves." (PMID 36357631, 2023). "However, until recently, there was no information regarding the effect of TGF-β on CCL2 chemokine expression in BC cells, and the association of increased TGF-β/Smad3 expression with CCL2 induction in smooth muscle cells is poorly translated to cancer cells." (PMID 34239022, 2021). "However, even with these limitations, many of the findings discussed have been validated by the fact that the same chemokine systems appear to be involved in mediating bone metastasis regardless of the cancer of origin, in particular CCL2/CCR2, CCL3/CCR1, IL-8/CXCR1, and CXCL12/CXCR4." (PMID 29930538, 2018).